TNC (tenascin C)
Diseases named in the same sentence as TNC in open-access papers (continued):
Sharing a sentence is not in itself a finding about the gene and the disease.
cholelithiasis (1 paper, 2020). The presence of crystallized deposits forming in the gallbladder or biliary tree, primarily composed of cholesterol, bilirubin, and bile. "Future studies should be directed to determine if tenascin-W, which shares a number of features with tenascin-C, plays a similar role in tumor stroma, or if the presence of tenascin-W during cholelithiasis could contribute to tumor progression." (PMID 33692777, 2020).
chronic asthma (1 paper, 2005). An asthma that is characterized by the development of persistent airway inflammation and recurrent attacks of breathlessness and wheezing, which vary in severity and frequency. "Upregulation of tenascin C and R, glycoproteins that contribute to extracellular matrix structure, may play an important role in airway remodeling, a characteristic of chronic asthma." (PMID 15661077, 2005).
chronic hepatitis (1 paper, 2020). An active inflammatory process affecting the liver for more than six months. "TNC deficiency reduced inflammation, TGF-β expression, and fibrosis in a murine chronic hepatitis model." (PMID 33217999, 2020).
chronic kidney disease (1 paper, 2022). Impairment of the renal function secondary to chronic kidney damage persisting for three or more months. "TNC pathway may serve as a potential therapeutic target for interstitial fibrosis and the progression of chronic kidney disease." (PMID 36522320, 2022).
chronic pancreatitis (1 paper, 2011). A chronic inflammatory process causing damage and fibrosis of the pancreatic parenchyma. "TNC expression is up-regulated in acute and chronic pancreatitis, and increases in the progression from low-grade precursor lesions (pancreatic intraepithelial neoplasia, PanIN) to PDAC." (PMID 21747918, 2011).
cleft palate (1 paper, 2020). Cleft palate is a fissure type embryopathy that affects the soft and hard palate to varying degrees. "Since TGF-β3 mutations are associated with cleft palate and bifid uvula in humans, we hypothesized that TGF-β regulates the expression of TNC in palatal mesenchyme." (PMID 32581832, 2020). "The initial studies of TNC-knockout mice did not report any obvious developmental abnormalities such as cleft palate, suggesting the existence of mechanisms that compensate for the loss of TNC." (PMID 32581832, 2020).
clubfoot (1 paper, 2022). The most common congenital deformation of the foot, occurring in 1 of 1,000 live births. "In our previous study, we detected changes in the composition of the ECM in the contracted M-side tissue of relapsed clubfoot—an increase in collagen III, V and VI, TGF-βIP, asporin, tenascin C, and qualitative changes in the distribution of TGF-β7." (PMID 35292718, 2022).
congenital myopathy (1 paper, 2025). "Pathogenic variants in the gene encoding fast skeletal TnC can cause mild congenital myopathy, highlighting the importance of TnC in the structure and function of skeletal muscle." (PMID 40218898, 2025).
congestive heart failure (1 paper, 2016). Failure of the heart to pump a sufficient amount of blood to meet the needs of the body tissues, resulting in tissue congestion and edema. "Furthermore, TnC L48Q mice did not have compromised relaxation and showed no sign of congestive heart failure." (PMID 26908229, 2016).
deafness (1 paper, 2024). An inherited or acquired condition characterized by the complete loss of the ability to hear from one or both ears. "In our case, a novel heterozygous mutation c.2852C>T (p.Thr951Ile) of the TNC gene in Chinese deafness families was not reported in the literature, which enriched the known TNC variant spectrum in HGMD Pro and PubMed databases." (PMID 38640279, 2024).
diffuse midline glioma (1 paper, 2019). A diffuse glioma that arises from the midline structures of the central nervous system. "Our findings suggest TNC overexpression in pediatric high grade and diffuse midline glioma is clinically detectable and may significantly contribute to tumor biology." (PMID 31092287, 2019). "Since H3K27 M mutation is associated with global changes in DNA methylation, altered chromatin structure, and poorer clinical outcomes in pediatric diffuse midline glioma, our findings suggest TNC overexpression in H3K27 M mutant tumors may be clinically and biologically relevant." (PMID 31092287, 2019).
dysplasia (1 paper, 2017). A usually neoplastic transformation of the cell, associated with altered architectural tissue patterns. "The increase from metaplasia to dysplasia was greater with tenascin-C, although only the difference between gastric metaplasia and high-grade dysplasia was statistically significant." (PMID 28978001, 2017). "Both tenascin-C and fibronectin were distinctly expressed in the lamina propria of normal esophageal mucosa covered by squamous epithelium and in the lamina or stroma of all evaluated lesion types, including intestinal and gastric metaplasia, low- and high-grade dysplasia and adenocarcinoma." (PMID 28978001, 2017).
endothelial dysfunction (1 paper, 2022). In vascular diseases, endothelial dysfunction is a systemic pathological state of the endothelium (the inner lining of blood vessels) and can be broadly defined as an imbalance between vasodilating and vasoconstricting substances produced by (or acting on) the endothelium. "Clearly, this testing outperforms other markers for endothelial dysfunction, such as galectin and tenascin-C, as well as ADMA, which is controversially discussed as mortality predictor." (PMID 35211826, 2022).
esophageal cancer (1 paper, 2016). A primary or metastatic malignant neoplasm involving the esophagus. "For this purpose, proteins were extracted from four patient matched normal and esophageal cancer tissues, and then western blot analyses were performed to determine the Tenascin-C isoform profiles and levels." (PMID 26731558, 2016). "In normal esophageal tissue, only one isoform of Tenascin-C (210 kDa) was identified, whereas at least three isoforms (210 kDa, 250 kDa, and 350 kDa) were found in esophageal cancer tissue." (PMID 26731558, 2016). "In addition, the Tenascin-C protein level was markedly higher in esophageal cancer tissues compared with normal tissues." (PMID 26731558, 2016). "Both 250 and 350 kDa sized isoforms of Tenascin-C were expressed only in esophageal cancer tissue not in normal tissue." (PMID 26731558, 2016).
Fuchs endothelial corneal dystrophy (1 paper, 2022). Fuchs endothelial corneal dystrophy (FECD) is the most frequent form of posterior corneal dystrophy (see this term) and is characterized by excrescences on a thickened Descemet membrane (corneal guttae), generalized corneal edema, with gradually decreased visual acuity. "In summary, the present study investigated the immunohistochemical expression pattern of tenascin-C, matrilin-2, and aggrecan in advanced forms of corneal endothelial pathology such as pseudophakic bullous keratopathy and Fuchs’ endothelial corneal dystrophy." (PMID 36294311, 2022).
gastrointestinal stromal tumor (1 paper, 2019). "However, few reports exist on TNC expression in gastrointestinal stromal tumors (GISTs)." (PMID 30633201, 2019).
Gliosis (1 paper, 2018). Gliosis is the focal proliferation of glial cells in the central nervous system. "Upregulation of Tenascin C has also been linked to growth factors and cytokines such as TGFβ1, interleukin 1 and TNFα, which have been associated with retinal degenerative disorders, suggesting that Tenascin C may contribute to gliosis." (PMID 30176221, 2018).
glomerulosclerosis (1 paper, 2025). A hardening of the kidney glomerulus caused by scarring of the blood vessels. "Tenascin-C (TNC), an extracellular matrix (ECM) glycoprotein, plays a crucial role in the development of TIF, while ECM deposition by activated mesangial cells is critical in glomerulosclerosis." (PMID 40869353, 2025).
granular type I corneal dystrophy (1 paper, 2012). "In granular type I corneal dystrophy, epithelial cells stained intensely for tenascin-C (p<0.0001 for both)." (PMID 22876117, 2012). "In conclusion, fibrillin-2 and tenascin-C are largely restricted to developing fetal tissues but become expressed again in granular type I corneal dystrophy and in lattice type I dystrophy." (PMID 22876117, 2012).
heart function (1 paper, 2016). "Using a model of impaired heart function (MI), the Ca2+ sensitized TnC L48Q was able to aid the diseased heart." (PMID 26908229, 2016).
Hodgkins lymphoma (1 paper, 2018). A heterogeneous group of malignant lymphoid neoplasms of B-cell origin characterized histologically by the presence of Hodgkin and Reed-Sternberg (HRS) cells in the vast majority of cases. "More recently, the F16 antibody directed to the extra-domain A1 of tenascin-C conjugated with 131I (Tenarad, PhilogenSpA, Siena, Italy) was tested in 8 patients with relapsed/refractory Hodgkin lymphoma." (PMID 29515769, 2018).
Hyperkeratosis (1 paper, 2021). Hyperkeratosis is a histopathological term defining a thickened stratum corneum and may be present in many different skin conditions, with many possible overlaps. "The overlapping DEGs included genes associated with hyperkeratosis (upregulated LCE3E and TMEM45A), wound healing (upregulated KRT17, IL36G, TNC, and TGFBI), barrier defects (downregulated FRAS1 and BCL11A), and response to infection (upregulated IL36G, ADAP2, DFNA5, RFTN1, LITAF, and TMEM173)." (PMID 34506598, 2021).
joint diseases (1 paper, 2020). "TNC is a key molecule in tissue remodeling, and its deregulated increased expression is linked to joint diseases, including OA and RA." (PMID 33072083, 2020).
juvenile idiopathic arthritis (1 paper, 2025). Juvenile idiopathic arthritis (JIA) is the term used to describe a group of inflammatory articular disorders of unknown cause that begin before the age of 16 and last over 6 weeks. "In children with active juvenile idiopathic arthritis, alterations in adiponectin, leptin, and tenascin C were observed, characterized by increased plasma ADPN and decreased LEP and TNC plasma concentrations, suggesting their involvement in the pathogenesis of JIA." (PMID 41011290, 2025).
knee osteoarthritis (1 paper, 2018). "In acute inflammatory arthritis and knee osteoarthritis, elevated tenascin-C promotes the expression of inflammatory factors and cartilage matrix degradation, both as a marker of joint damage and as a promoter of joint destruction." (PMID 30442110, 2018).
lattice type I corneal dystrophy (1 paper, 2012). "Fibrillin-2, tenascin-C, matrilin-2, and matrilin-4 may be markers of the pathogenesis of either granular or lattice type I corneal dystrophy, as revealed by immunohistochemical analysis." (PMID 22876117, 2012). "Fibrillin-2, tenascin-C, matrilin-2, and matrilin-4 may be characteristic of the pathogenesis of either the granular or lattice type I corneal dystrophy, as revealed by immunohistochemical analysis." (PMID 22876117, 2012).
lymphedema (1 paper, 2025). Excess fluid collection in tissues, causing swelling. "Consistent with the tail lymphedema model, the number of lymphatic vessels was significantly increased in TNC−/− mice." (PMID 39925433, 2025). "TNC−/− mice showed smaller tail diameters and a thinner dermis/epidermis than WT mice with tail lymphedema." (PMID 39925433, 2025). "We found an inverse correlation between lymphangiogenesis and TNC expression in a mouse lymphedema model." (PMID 39925433, 2025). "Collectively, these results indicate that the genetic deletion of TNC promoted the growth of lymphatic vessels and ameliorated lymphedema as well as inflammation." (PMID 39925433, 2025). "To determine whether TNC functions as a negative regulator of lymphangiogenesis and modulates inflammatory responses, we compared wild-type (WT) mice and TNC knock-out (TNC−/−) mice in the tail lymphedema model." (PMID 39925433, 2025). "Therefore, we initially clarified the temporal expression and spatial localization of TNC molecules and lymphatic vessels in the tail lymphedema mouse model." (PMID 39925433, 2025).
male infertility (1 paper, 2023). The inability of the male to effect fertilization of an ovum after a specified period of unprotected intercourse. "Thus, we wonder how to evaluate the regulatory mechanism between MKRN2 and STAT1/SIX4/TNC to figure out the novel mechanism of MKRN2 in male infertility." (PMID 36967804, 2023). "In this study, we found a new regulatory mechanism between MKRN2 and STAT1/SIX4/TNC, which is a novel mechanism of MKRN2 in regulating male infertility." (PMID 36967804, 2023). "In this study, we plan to address: (a) the role of MKRN2 in male infertility; (b) whether MKRN2 regulates the expression level of STAT1; and (c) how MKRN2 induces the expression levels of SIX4 and TNC by the transcription factor EBF transcription factor 2 (EBF2)." (PMID 36967804, 2023).
mitral valve disease (1 paper, 2021). "High blood lactate concentrations were investigated in dogs with mitral valve disease stage C compared with stage B. The peptides such as mitogen-activated protein kinase, kallikrein, and tenascin-C appeared in the heart disease progression group." (PMID 35127880, 2021).
Multiple myeloma (1 paper, 2022). "Multiple myeloma cells, however, attached only weakly to tenascin-C, although this protein was prominently expressed in the BM of multiple myeloma patients." (PMID 34838648, 2022).
myoma (1 paper, 2018). "After analysing myoma from more than 150 patients, we may conclude that the greater the amount of tenascin-C within the myoma discs, the deeper the cancer cells invade." (PMID 29158312, 2018).
nasal polyps (1 paper, 2021). "Our data addresses the knowledge gap and suggests that besides tissue remodeling, tenascin C has the potential to enhance the inflammation within nasal polyps." (PMID 34504680, 2021). "Periostin is a confirmed novel biomarker for the formation of nasal polyps and tenascin C is an indicator of inflammation." (PMID 34504680, 2021). "We also found higher levels of periostin in nasal polyps compared with the controls and higher levels of tenascin C in nasal polyps compared with CRSsNP and the controls." (PMID 34504680, 2021). "Additionally, periostin and tenascin C have been reported to stimulate the expression of MMPs beyond nasal polyps." (PMID 34504680, 2021). "In this context, we speculated that periostin and tenascin C might be able to regulate the expression of these MMPs within nasal polyps." (PMID 34504680, 2021). "Periostin and tenascin C might be involved in the remodeling of nasal polyps by regulating the expression of different MMPs in epithelial cells and fibroblasts." (PMID 34504680, 2021). "Thus, we investigated the roles of periostin and tenascin C in promoting the expression of MMPs via fibroblasts and the nasal epithelium in nasal polyps." (PMID 34504680, 2021). "We identified that there is a positive correlation of periostin and tenascin C with MMPs and found that periostin and tenascin C could stimulate the ex vivo expression of MMPs mainly in different cells derived from nasal polyps, periostin in fibroblasts and tenascin C in epithelial cells." (PMID 34504680, 2021). "Given the roles of periostin and tenascin C in promoting the expression of MMPs in CRSwNPs, our results indicate that anti‐periostin or anti‐tenascin C treatment might be able to inhibit tissue remodeling within nasal polyps, which still needs to be further verified by in vivo animal studies." (PMID 34504680, 2021). "However, the regulatory role of tenascin C on MMPs in nasal polyps remains unknown." (PMID 34504680, 2021).
non-alcoholic fatty liver disease (1 paper, 2017). "Similarly, increases in hepatic tenascin-C expression occur in obese individuals with non-alcoholic fatty liver disease (NAFLD), and in each of these scenarios tenascin-C interacts with TLR4 to augment local tissue inflammation." (PMID 29137117, 2017).
obstructive sleep apnea (1 paper, 2025). "Moreover, the association between TnC, TSP-1, and obstructive sleep apnea is also worth exploring." (PMID 41010873, 2025).
oral lichen planus (1 paper, 2023). Oral lichen planus is a chronic inflammatory oral condition of unknown aetiology characterized by T-cell-mediated chronic immune response and abnormal epithelial keratinization cycle. "In a study of oral lichen planus (OLP) and normal skin tissues performing RNA-seq, molecules related to wound healing, KRT17, IL36G, TNC and TGFBI genes were significantly upregulated in OLP tissues." (PMID 37929023, 2023).
ovarian endometriosis (1 paper, 2021). A non-neoplastic disorder characterized by the growth of endometrial tissue in the ovaries. "On the other hand, patients with pelvic endometriosis, with or without ovarian involvement, may have a higher prevalence of tenascin-C autoantibodies than patients with isolated ovarian endometriosis." (PMID 33660232, 2021).
peritoneal adhesions (1 paper, 2025). "The increased expression of tenascin-C has been observed in peritoneal adhesions and is associated with tissue fibrosis and impaired wound healing." (PMID 40699873, 2025). "One possible treatment approach for avoiding or decreasing the production of peritoneal adhesions is to modify the expression or activity of tenascin-C." (PMID 40699873, 2025).
pleural mesothelioma (1 paper, 2021). A neoplasm that arises from the mesothelial cells of the pleura. "We collected the methylation profile of pleural mesothelioma, and found 8 novel interactors to be hypomethylated in pleural mesothelioma versus non-tumor pleural tissue, namely, ACVR1B, IL6, MGMT, NRG1, OAT, PHLDA2, PLAUR and TNC." (PMID 33916178, 2021).
prostate adenocarcinoma (1 paper, 2019). "TCGA prostate adenocarcinoma cases with TNC alteration also demonstrated prominent decrease in disease-free survival (P = 0.0637)." (PMID 31798767, 2019).
psychosis (1 paper, 2020). "Significantly lower levels of TNC protein, which has crucial roles in different aspects of neurodevelopment, were recently observed in the dorsolateral prefrontal cortex (DLPFC) of BD patients with a psychosis history compared to non-psychotic BD subjects." (PMID 33276438, 2020).
pterygium (1 paper, 2022). A wedge-shaped fibrovascular lesion arising from the bulbar conjunctiva and extending to the cornea. "It was reported that TNC mRNA is a target of miR-9-5p and is involved in pterygium development." (PMID 36398070, 2022). "Among those DE-mRNAs, matrix metallopeptidase 3(MMP-3), fibronectin 1 (FN1), tenascin C (TNC), LRRC15, KRT6A, COMP, AKR1B10, and MUC5AC were significantly upregulated, which was consistent with previous studies on pterygium." (PMID 36398070, 2022).
Pulmonary hypoplasia (1 paper, 2013). "SHAM fetuses showed neither real pulmonary hypoplasia nor significant changes in elastin deposition, but sensitive qPCR could detect differences for TNC, TIMP2, and MMP2/TIMP1 ratio." (PMID 23840910, 2013).
retinal diseases (1 paper, 2023). "Tenascin-C upregulation has also been associated with ischemia-associated retinal degeneration and vascular disorder associated-retinal diseases such DR with the latter known to affect the retinal microvascular circulation." (PMID 36936905, 2023).
rheumatic fever (1 paper, 2018). A post-bacterial multisystem inflammatory disease occurring as a post-infectious, nonsuppurative sequela of untreated streptococcus pyogenes (Group A streptococcus [GAS]) pharyngitis, and mainly occurs in individuals aged 5 to 15 years. "Our quantitative analyses suggest that this immune activation may persist long after a bout of rheumatic fever and ultimately lead to ECM remodelling in association with expression of tenascin-C." (PMID 30261069, 2018).